SENP2 (SUMO specific peptidase 2)
Diseases named in the same sentence as SENP2 in open-access papers (continued):
Sharing a sentence is not in itself a finding about the gene and the disease.
colitis (1 paper, 2023). Inflammation of the colon. "Consistent with this, the loss of SENP2 caused more severe colitis as the length of the colon, measured at day 14 after DSS induction, decreased in CKO mice, while WT and CKO mice had similar colon lengths after H2O treatment." (PMID 37301920, 2023). "Therefore, we tested whether Senp2 deficiency in T cells affects the progression of DSS-induced colitis." (PMID 37301920, 2023). "Adoptive transfer experiments demonstrate the cell-autonomous effect of Senp2 in restraining Th17 differentiation and colitis." (PMID 37301920, 2023). "Taken together, these results suggested that the progression of DSS-induced colitis was enhanced in the absence of Senp2 in T cells, which is linked to the increased generation of pathogenic Th17 cells." (PMID 37301920, 2023). "Our results again show that the presence of Senp2 in Th17 cells reduces colitis." (PMID 37301920, 2023). "By deleting Senp2 in T-cell lineages in mice, we demonstrate that the lack of Senp2 exacerbates the severity of experimental colitis, which is linked to elevated levels of GM-CSF+IL-17A+ pathogenic Th17 cells and more severe dysbiosis of the intestinal microbiome." (PMID 37301920, 2023).
epilepsy (1 paper, 2020). A brain disorder characterized by episodes of abnormally increased neuronal discharge resulting in transient episodes of sensory or motor neurological dysfunction, or psychic dysfunction. "Given that SENP2 has been implicated in neural disorders such as epilepsy and neurodegeneration, future studies should be directed to examine the role of these SENP2-regulated molecular pathways in the observed behaviors." (PMID 32290845, 2020).
glucocorticoid deficiency (1 paper, 2022). "As a result, foetal or postnatal deletion of Senp2 in adrenal steroidogenic cells causes postnatal hypoplasia limited to the zF or incomplete zF formation respectively, which can lead to isolated glucocorticoid deficiency." (PMID 36543805, 2022). "Disruption of SENP2 activity in steroidogenic cells leads to specific hypoplasia of the zona fasciculata, a blunted reponse to ACTH and isolated glucocorticoid deficiency." (PMID 36543805, 2022). "As a result, in the absence of NaCl supplementation, Senp2,Prkar1adcKO mice died prematurely from salt wasting, whereas Senp2cKO mice only suffered from isolated glucocorticoid deficiency." (PMID 36543805, 2022).
head and neck carcinoma (1 paper, 2024). A carcinoma that arises from the head and neck region. "To investigate a functional link between the loss of SENP2 and the MDC in aggressive carcinomas, we made use of two head and neck carcinomas explanted in vitro." (PMID 39152119, 2024). "Consistently, metastatic head and neck cancer cells that do not respond to the mitosis-differentiation checkpoint were resistant to depletion of SENP2." (PMID 39152119, 2024).
heart failure (1 paper, 2022). Inability of the heart to pump blood at an adequate rate to meet tissue metabolic requirements. "Since enhanced deSUMOylation in murine hearts through overexpression of SENP2 led to congenital heart defects and cardiac dysfunction, we require inhibitor(s) which efficiently bind to SENP2, inhibit SENP2, and are used for heart failure treatment." (PMID 35431915, 2022). "Then due to its significant role in the development of many diseases especially heart failures, SENP2 can be an attractive target for drug discovery." (PMID 35431915, 2022). "This is an in silico study to inhibit SENP2 by natural products for use in heart failure treatment." (PMID 35431915, 2022). "Therefore, depending upon the outcomes presented herein, Betanin significantly inhibited SENP2 and hence may be considered as a suitable natural compound for the treatment of heart failure." (PMID 35431915, 2022).
Hypertension (1 paper, 2023). The presence of chronic increased pressure in the systemic arterial system. "Among the downregulated genes, GNB3 is associated with hypertension and SENP2 with newborn health issues." (PMID 38681774, 2023). "Downregulation of genes such as GNB3, SENP2, and YTHDC2 highlights potential links to hypertension, early mortality, and male fertility issues." (PMID 38681774, 2023).
multiple myeloma (1 paper, 2020). "Taken together, we report that silencing of SENP2 and consequent activation of NF-κB through the modulation of IκBα sumoylation as a novel mechanism inducing bortezomib resistance in multiple myeloma." (PMID 31964975, 2020). "Furthermore, down regulation of SENP2 in multiple myeloma cell line RPMI8226 alleviated bortezomib induced cell proliferation inhibition and apoptosis, whereas, overexpression of SENP2 sensitized these cells to bortezomib treatment." (PMID 31964975, 2020). "In this study, by combining in silico analysis and sgRNA library based drug resistance screening assay, we identified SENP2 (Sentrin/SUMO-specific proteases-2) as a bortezomib sensitive gene and found its expression highly downregulated in bortezomib resistant multiple myeloma patient’s samples." (PMID 31964975, 2020).
Myocardial fibrosis (1 paper, 2025). "IGFBP6 may also aggravate myocardial fibrosis by regulating SENP2 maturation of myocardial fibroblasts, thereby regulating cholesterol flow." (PMID 41208894, 2025).
pulmonary fibrosis (1 paper, 2023). Chronic progressive interstitial lung disorder characterized by the replacement of the lung tissue by connective tissue, leading to progressive dyspnea, respiratory failure, or right heart failure. "Even in static conditions, the Z-score of the pulmonary fibrosis idiopathic signaling pathway remains positive, further suggesting the pro-fibrotic effects of the phospho-site mutation SENP2 S344A KI MLECs." (PMID 37711550, 2023).
cancer (16 papers, 2013 to 2025). A tumor composed of atypical neoplastic, often pleomorphic cells that invade other tissues. "Alterations of SENP2 expression have been associated with some types of cancer." (PMID 39152119, 2024). "This also might explain why both alterations of SENP2 have been found associated with some cancers." (PMID 39152119, 2024). "In this study, we show that SUMO conjugation or deconjugation specifically mediated by SENP-1 and SENP-2 proteases represents a novel regulatory mechanism of GRHL2-dependent transcriptional activity in cancer cells." (PMID 40889682, 2025). "SENP1 and SENP2 have been commonly studied in terms of their function in cancer progression among other SENP enzymes." (PMID 40434722, 2025). "Previous investigations have established that SENP2 assumes an anti-tumorigenic role across a spectrum of malignancies." (PMID 39578257, 2024). "Our results revealed that the suppression of ERK2 effectively rescued the enhanced colony formation ability, migration, and EMT process of cancer cells triggered by SENP2 overexpression in MDA-MB-231 cells." (PMID 39578257, 2024). "As we knew little about the SENP2 functions, our results provide mechanisms by which its alteration can contribute to cancer." (PMID 39152119, 2024). "Altogether, our data show how SENP2 regulates its substrate for desumoylation, and also the role of SENP2 in TGF-β induced cancer cell migration." (PMID 29955155, 2018). "However, the studies exploring the anti-cancer potential of SENP2 inhibitors such as NSC632839 is very limited in the literature." (PMID 40434722, 2025). "These roles of SENP2 give a hint about the involvement of SENP2 in cancer progression." (PMID 40434722, 2025). "Additionally, SENP2 upregulates the migration of breast cancer cells and contributes to cancer stemness by regulating transforming growth factor (TGF)-β/Smad4-dependent signaling." (PMID 38280996, 2024). "In cancer cells, SENP2 is a potential tumor suppressor because it negatively regulates the proliferation, invasion, and migration of osteosarcoma cells by promoting ubiquitination and degradation of SRY-box-9 (SOX9), a transcription factor required during embryonic development." (PMID 38280996, 2024). "Similarly, in breast cancer, it has also been shown that SENP2 inactivates NF-κB, sensitizing cancer cells to doxorubicin." (PMID 35887358, 2022). "Similarly, SENP2 aberrant activity influenced several transcription factors participating in cancer development and progression." (PMID 33923236, 2021). "Combining with previous studies, it could be deduced that SENP2 was a tumor suppressor in various cancers; however, studies should be further conducted to verify this." (PMID 34950583, 2021). "While the mechanisms controlling SENP2 expression in cancers remain unknown, NF-κB shown to induce the expression of SENP2 under genotoxic stress condition." (PMID 31964975, 2020). "The distinct outcomes of SENP2 in regulating cell migration and invasion could be due to different cellular contexts of cancer cells." (PMID 29955155, 2018). "Moreover, and contrary to the rapid differentiation response following SENP2 depletion in non-transformed epithelial cells, aggressive carcinoma cells were resistant to loss of SENP2." (PMID 39152119, 2024). "Therefore, it is reasonable to hypothesize that SENP2, as an enzyme, inhibits SUMOylation and suppresses the progression of several cancers, including HCC." (PMID 34950583, 2021). "Besides, SENP2 is also regarded as an anti-oncogene in several cancers." (PMID 34950583, 2021). "Thus, SENP2 plays a critical role in overcoming drug resistance in cancers." (PMID 31964975, 2020).
cancer (continued). "Despite constitutive expression of NF-κB in cancers, SENP2 expression is found silenced, indicating additional epigenetic mechanisms operating in silencing of SENP2 expression, which could therefore serve as attractive targets for treating bortezomib resistant MM." (PMID 31964975, 2020). "In our study, the anti-cancer effect of NSC632839 in PCa was studied for the first time in the literature and also the expression level of SENP2 and its correlation with the androgen receptor (AR) in PCa tissue samples were evaluated using public databases." (PMID 40434722, 2025). "Similarly, the key genes SNW1, SENP2 and SMNDC1 identified in this study in the context of acquired resistance, have previously been implicated in cancer cell proliferation, death, and metastasis, although their specific role in regulating platinum resistance remains unknown." (PMID 38957470, 2024). "By specifically targeting SENP2-mediated deSUMOylation of ERK2, we aim to modulate its activity selectively in cancer cells where SUMOylation machinery is dysregulated." (PMID 39578257, 2024). "In GC cells, it has been shown that overexpression of SENP2 desumoylates and stabilizes NDRG2, which results in inhibition of cancer cell proliferation." (PMID 35887358, 2022). "Few exceptions include SENP2 and PIAS2, which consistently show downregulated expression in cancer cells and correlate with better prognosis when overexpressed." (PMID 35887358, 2022). "In breast cancer cells, SENP2 participated in the regulation of estrogen receptor α (ERα) signaling and transforming growth factor (TGF-β) signaling, which modulated cancer cell proliferation, migration, and invasion." (PMID 33923236, 2021). "Significantly, we discovered that SENP2 is involved in the post-translational modification of ERK2 through SUMOylation, which plays a critical role in stabilizing the protein and curbing EMT, a key process in cancer metastasis." (PMID 39578257, 2024). "As conclusion, alteration of SENP2 function in the MDC, might contribute to genomic instability and explain the positive or negative association of SENP2 with cancer." (PMID 39152119, 2024). "Our data show that SENP2 is highly expressed in breast cancer tissues compared to normal tissues, providing an opportunity to selectively target the SENP2-ERK2 axis in cancer cells." (PMID 39578257, 2024).
tumor (13 papers, 2016 to 2024). "We silenced SENP2 in either tumour by shSP2 and determined the loss of proliferative capacity." (PMID 39152119, 2024). "The Notch signaling pathway and MYC targets play broad roles in the promotion or inhibition of proliferation and cell death, related to the regulatory role of SENP2 in tumor growth." (PMID 38957470, 2024). "Notably, SENP2 knockdown significantly curtailed the initiation and progression of subcutaneous xenografts in these mice, as evidenced by the growth curve and tumor weight." (PMID 39578257, 2024). "Sentrin-specific protease-2 (SENP2) could act as a tumor suppressor in CLL cells via suppressing the Notch and NF-κB signaling pathways." (PMID 39092224, 2024). "We propose that SENP2 inhibition could be used to decrease cytoplasmic p21 localization and, consequently, promote its tumour suppressive role." (PMID 28582471, 2017). "Further subgroup analyses indicated that SAE1 and UBE2I had differential expressions with different stages, while SENP1, USPL1, SENP2, SENP5, SAE1, UBA2, and UBE2I had differential expressions with different tumor grades." (PMID 34267779, 2021). "SENP2 expression in HCC tumor tissues and adjacent tissues was detected by IHC, which revealed that SENP2 IHC score was reduced in tumor tissues compared with adjacent tissues (p < 0.05)." (PMID 34950583, 2021). "We checked the distribution of genotypes and frequency of alleles of the SENP1 and SENP2 genes polymorphisms in groups of patients with different hormone receptor status, patients with positive and negative lymph node status and patients with different tumor grade." (PMID 27178176, 2016). "We also checked the distribution of genotypes and frequency of alleles of the SENP1 and SENP2 genes polymorphisms in groups of patients with different hormone receptor status, patients with positive and negative lymph node status and patients with different tumor grade." (PMID 27178176, 2016). "Remarkably, SENP2 knockdown significantly inhibited the growth of MDA-MB-231 and MCF-7 cells, whereas exogenous overexpression of SENP2 significantly enhanced the growth of tumor cells." (PMID 39578257, 2024). "Antigen-specific CD8+ Tn cells from Vegfb WT or -cKO OT-1 mice were activated by OVA257–264 peptide followed by lentivirus-mediated Senp2 overexpression, and then these OT-1 T cells were adaptively transferred to recipient mice with MC38-OVA tumor cells inoculated." (PMID 39145452, 2024). "Moreover, SENP1, USPL1, SENP2, SENP5, SAE1, UBA2, and UBE2I had differential expressions with different tumor grades." (PMID 34267779, 2021). "In addition, the recipient mice transplanted with Senp2-overexpressed Vegfb-cKO OT-1 cells had slower tumor growth compared with the negative control mice." (PMID 39145452, 2024). "We did not observe any association between: progesterone receptor status, HER2 expression and tumor grade described by Bloom-Richardson grading system, and the distribution of genotypes and frequency of alleles for these polymorphisms of the SENP1 and SENP2 genes (data not shown)." (PMID 27178176, 2016).
infection (3 papers, 2022 to 2024). The state of being infected such as from the introduction of a foreign agent such as serum, vaccine, antigenic substance or organism. "At the later infection stage, SENP2 removes SUMO conjugates to facilitate RIG-I and MDA5 proteasomal degradation to terminate RNA sensing signaling." (PMID 35795661, 2022). "However, during the late phase of infection, de-SUMOylation of RIG-I and MDA5 by sentrin/SUMO-specific protease 2 (SENP2) triggers their proteasomal degradation, aiding in finishing the pro-inflammatory response once the virus has been cleared." (PMID 39431052, 2024).
metabolic disorders (2 papers, 2016 to 2025). "Given the considerable amount of metabolically active BAT present in adult humans, SENP2 in BAT may serve as a therapeutic target to treat metabolic disorders." (PMID 40579429, 2025).
neurodegenerative disease (2 papers, 2014 to 2022). A disorder of the central nervous system characterized by gradual and progressive loss of neural tissue and neurologic function. "Testing the protective role of SENP2 in neural cell survival in disease conditions is also likely to gain a knowledge base of neurodegenerative diseases, leading to new therapeutic strategies." (PMID 25299344, 2014). "A disruption of SENP2 in a specific neuronal subtype may further divulge its role in neurodegenerative diseases." (PMID 25299344, 2014). "Exploring the protective effect of SENP2 on neuronal cell death may uncover important preventive and therapeutic strategies for neurodegenerative diseases." (PMID 25299344, 2014).
gastrointestinal tumors (1 paper, 2023). "Studies suggested that non-canonical PTMs such as SENP2 mediated de-SUMOylation of N-myc, Mdm2 regulated neddylation of HuR, and PADI4 promoted histone citrullination of NETs contribute to the progression of gastrointestinal tumors." (PMID 37777749, 2023).
heart disease (1 paper, 2022). "Then, natural compounds can be suitable inhibitors and since SENP2 is a protein involved in heart disease, so our aim was inhibition of SENP2 by natural products for heart disease treatment." (PMID 35431915, 2022). "Then, our aim was the selection of compounds with more affinity, among natural compounds, for decreasing SENP2 expression for the treatment of heart disease." (PMID 35431915, 2022).
SENP2 also shares sentences with these, for which no sentence is quoted: endothelial dysfunction (2 papers); Insulin resistance (2); colorectal cancer (1); Impaired glucose tolerance (1); ischemia (1); lymphoma (1); metabolic syndrome (1); pericardial effusion (1).